GPC2 (glypican 2)
Description:
Cell surface proteoglycan that bears heparan sulfate. May fulfill a function related to the motile behaviors of developing neurons (By similarity).
Synonyms: cerebroglycan; FLJ38962; DKFZp547M109
Tractability: Antibody: its Gene Ontology location is reachable by antibodies, with high confidence; UniProt places it where antibodies can reach, with medium confidence; UniProt predicts a signal peptide or a membrane-spanning region. PROTAC: its protein half-life has been measured.
Gene: Protein-coding gene on chromosome 7 (100,169,606 to 100,177,381, reverse strand). Ensembl gene ENSG00000213420.
Subcellular location: Cell membrane; Secreted, extracellular space (Secreted glypican-2)
Pathways (Reactome):
Disease: Attachment and Entry; Defective B3GALT6 causes EDSP2 and SEMDJL1; Defective B3GAT3 causes JDSSDHD; Defective B4GALT7 causes EDS, progeroid type; Defective EXT1 causes exostoses 1, TRPS2 and CHDS; Defective EXT2 causes exostoses 2; Dengue Virus Attachment and Entry; Dengue Virus-Host Interactions; RSV-host interactions; Respiratory syncytial virus (RSV) attachment and entry
Metabolism: Glycosaminoglycan-protein linkage region biosynthesis; HS-GAG biosynthesis; HS-GAG degradation
Hemostasis: Initiation of coagulation cascade; Regulation of clotting cascade
Sensory Perception: Retinoid metabolism and transport
Gene Ontology:
Molecular function: protein binding
Biological process: cell migration; positive regulation of neuron projection development; regulation of protein localization to membrane; smoothened signaling pathway; neuron differentiation; regulation of signal transduction
Cellular component: endoplasmic reticulum; cell surface; extracellular matrix; Golgi lumen; lysosomal lumen; plasma membrane; synapse; extracellular region
Genetic constraint (gnomAD): Loss-of-function variants: 42 observed, 50.18 expected, observed/expected ratio (o/e) 0.84, 90% interval 0.65 to 1.08. The upper end of that interval is the gene's LOEUF score, 1.08, which puts it in group 4 of 6, group 1 being the genes least tolerant of losing a copy. Missense variants: 745 observed, 720.36 expected, observed/expected ratio (o/e) 1.03, 90% interval 0.97 to 1.1. Synonymous variants: 364 observed, 304.52 expected, observed/expected ratio (o/e) 1.2, 90% interval 1.1 to 1.3.
Homologues: Orthologues: chimpanzee GPC2 (99% identical), macaque GPC2 (97% identical), mouse Gpc2 (82% identical), rat Gpc2 (82% identical), guinea pig GPC2 (80% identical), pig GPC2 (75% identical), dog GPC2 (71% identical), tropical clawed frog gpc2 (44% identical), Drosophila melanogaster dlp (27% identical), zebrafish gpc2 (26% identical). Paralogues in human: GPC6 (40% identical), GPC4 (37% identical), GPC1 (37% identical), GPC5 (21% identical), GPC3 (19% identical).
Diseases named in the same sentence as GPC2 in open-access papers:
GPC2 is named in the same sentence as 59 diseases in open-access papers, as found by Europe PMC text mining. Sharing a sentence is not in itself a finding about the gene and the disease. The quoted sentences say what the papers report.
neuroblastoma (51 papers, 2018 to 2026). Neuroblastoma (NB) is the most common solid, extracranial childhood tumor. "Further studies have employed computational approaches to identify the immunotherapy targets such as CAMKV in neuroblastoma patients presenting with MYCN or GPC2 amplification in high-risk neuroblastoma." (PMID 36295546, 2022). "GPC2, encoding Glypican 2, is a member of the glypican family genes that produce proteoglycan with a glycosylphosphatidylinositol anchor and is a cell surface oncoprotein in neuroblastoma." (PMID 39103522, 2024). "Glypican-2 is upregulated in neuroblastoma and associated with poor overall survival." (PMID 31620357, 2019). "GPC2-directed allogeneic CAR-T cells demonstrated enhanced or comparable activity relative to conventional lentiviral CAR-T cells in neuroblastoma models and mediated tumor regression with prolonged survival in preclinical models." (PMID 42094429, 2026). "Exosomes, nanoscale extracellular vesicles secreted by the tumor cells, exhibit natural tropism and can be engineered to selectively target neuroblastoma-specific biomarkers such as glypican-2 (GPC2), which is highly expressed in MYCN-amplified tumors." (PMID 41750126, 2026). "Previous studies have demonstrated the efficacy of GPC2-targeted CAR T cells in neuroblastoma and medulloblastoma." (PMID 40517137, 2025). "Accordingly, AbTCR T cells induced rapid and enhanced regression of IMR5 and NBEB neuroblastoma xenografts (1,729–2,180 GPC2 molecules per cell) in mice within 1 or 2 weeks." (PMID 41027430, 2025). "Both CT3 and hCT3 AbTCR T cells show superior antitumor efficacy compared to CT3 CAR T cells, with hCT3 AbTCR T cells inducing significant regression in neuroblastoma with low GPC2 antigen density." (PMID 41027430, 2025). "Crystal Mackall’s group developed a suite of low-affinity GPC2-CARs, optimized for targeting tumors and decreasing toxicity, demonstrating efficacy in preclinical neuroblastoma models." (PMID 40517137, 2025). "Glypican-2 (GPC2) is an oncofetal antigen highly expressed in neuroblastoma and under evaluation in phase 1 clinical trials." (PMID 41027430, 2025). "To evaluate the effect of MIF on tumor cell killing by GPC2 CAR-T cells, we quantified CAR-T cell killing capacity against MIF-deficient neuroblastoma cells (SK-N-BE2C-shMIF) in co-cultures." (PMID 39908652, 2025). "Recent studies have highlighted differences in GPC2 transcript expression between neuroblastoma cells and normal tissues, suggesting the existence of a tumor-selective GPC2 sequence that can be targeted specifically to the tumor." (PMID 40104501, 2025). "GPC2’s selective expression to neuroblastoma makes it an attractive target for immunotherapy, particularly for CAR-T therapies, as a means to enhance neuroblastoma cell specificity and limit cytotoxicity to normal cells." (PMID 40104501, 2025). "This study highlights the superior antitumor efficacy of the AbTCR T cell platform and its potential clinical utility of GPC2-targeted hCT3 AbTCR T cells for treating neuroblastoma." (PMID 41027430, 2025). "These CAR-T cells demonstrated potent anti-tumor activity against neuroblastoma cells that express high levels of GPC2, making it a promising target for neuroblastoma therapy." (PMID 40069884, 2025). "To investigate the roles of MIF and MDK on CAR T-cell modulation, we used CAR T-cells targeting GPC2, which have shown robust safety and efficacy in diverse preclinical models of neuroblastoma and are currently being tested clinically (NCT05650749)." (PMID 39908652, 2025). "GPC2 is expressed on the surface of neuroblastoma cells, activating the WNT signaling pathway and stimulating growth." (PMID 40104501, 2025). "While GPC2-CAR T cells have already demonstrated efficacy in neuroblastoma models, our findings support their inclusion as a potential therapy for pediatric HGGs." (PMID 40517137, 2025).
neuroblastoma (continued). "CT3 CD28HTM, the most potent CAR construct we have developed for targeting GPC2-expressing neuroblastoma, is currently being developed for a clinical trial." (PMID 41027430, 2025). "Using a bicistronic construct GPC2.CD28ζ+/− GLUT1 CAR-T cells were co-cultured with neuroblastoma cell lines expressing ~34,000 (NGP-GPC2) or 6800 (SMS-SAN) molecules of GPC2 on the surface." (PMID 39370422, 2024). "GPC2 is over-expressed on neuroblastoma, as well as a variety of other cancers such as small-cell lung cancer, osteosarcoma and Ewing sarcoma." (PMID 39489087, 2024). "More importantly, GPC2 was minimally expressed in normal tissues, making it an attractive target for immunotherapy of neuroblastoma." (PMID 39014225, 2024). "Recently reports demonstrate that the expression of GPC2 is significantly increased in multiple childhood cancers, including neuroblastoma." (PMID 35233466, 2022). "Other scholars found that the expression of GPC2 is significantly increased in neuroblastoma an undetectable in normal tissues, including the brain, heart, lung, and kidney, indicating that GPC2 is a suitable tumor antigen in neuroblastoma." (PMID 35233466, 2022). "GPC2 belongs to a six-member human glypican family of proteins and is highly expressed in neuroblastoma." (PMID 35281080, 2022). "These researchers also reported that CRISPR/Cas9- or siRNA-mediated inhibition of GPC2 expression suppresses the outgrowth of neuroblastoma tumor cells." (PMID 35468841, 2022). "Compared with single target CAR T cells, BiCisCAR T cells not only had comparable in vitro cytotoxicity against neuroblastoma cells coexpressing GPC2 and CD276, but they also secreted greater amounts of cytokines, such as IFN-γ and TNF-α." (PMID 35968786, 2022). "A recent study has revealed that GPC-2 can positively regulate Wnt signaling in neuroblastoma, as silencing of GPC-2 inactivates Wnt/b-catenin signaling and reduces the expressions of target genes." (PMID 33902495, 2021). "At an effector:target ratio of 8:1, GPC2-specific CAR-T cells reveal the cytotoxicty against IMR5 neuroblastoma cells ranged from 44% to 71%, with an average of 56%." (PMID 33567640, 2021). "GPC2-specific CAR-T cells can efficiently lytic IMR5 neuroblastoma cells with high-level expression of GPC2." (PMID 33567640, 2021). "Hereby, GPC2 protein is highly expressed in brain tumors, which had been validated in neuroblastoma." (PMID 32802843, 2020). "We previously reported that MYCN mediates GPC2 expression in neuroblastoma and that GPC2 was overexpressed in neuroblastomas that have 7q gains, where the GPC2 locus is." (PMID 32211329, 2020). "Here we found that neurospheres derived from neuroblastoma stem-like cells showed a homogeneous staining for several key nucleolar proteins, such as Nucleolin, Nucleophosmin-1, Glypican-2 and PES-1." (PMID 32737364, 2020). "High expression of GPC2 has been detected in neuroblastoma and other pediatric cancers such as medulloblastoma and retinoblastoma." (PMID 32916872, 2020). "Two forms of antibody therapeutics targeting GPC2 have been successfully developed for neuroblastoma treatment." (PMID 32916872, 2020). "The high expression of GPC2 on the neuroblastoma cell surface brought promising clearance of disseminated neuroblastoma in the mouse model by anti-GPC2 CAR T cells." (PMID 33322408, 2020). "The related glypican 2 (GPC2), however, has been shown to be an oncoprotein and immunotherapeutic target in high risk neuroblastoma." (PMID 30873384, 2019). "Monoclonal antibodies targeting GPC-2 have been developed as a therapeutic for neuroblastoma, and antibodies targeting GPC-3 have progressed to phase I trials in HCC." (PMID 32010611, 2019). "Retrospective review demonstrated significantly decreased survival in neuroblastoma patients with tumors expressing high levels of GPC2." (PMID 30459759, 2018).
neuroblastoma (continued). "Though this study needs to be expanded to include a broader array of neuroblastoma cell lines and primary human samples, preliminary data suggest that GPC2 should be further evaluated as a clinical target for CAR T cell therapy in neuroblastoma." (PMID 30459759, 2018). "Notably, hCT3 AbTCR T cells caused significant tumor regression of low-antigen-density neuroblastoma, including the subcutaneous mouse model using LAN1 (472 GPC2 molecules per cell) and the orthotopic mouse model using SH-SY5Y (581 GPC2 molecules per cell)." (PMID 41027430, 2025). "SCAN-ACT identified 174 monospecific CAR-T targets in GBM, including several established GBM CAR-T targets such as CD276, EGFR, IL13RA2, ROBO1, as well as targets studied in different diseases like GPC2 in neuroblastoma, IL11RA in osteosarcoma, or DLL3 in lung cancer." (PMID 40814001, 2025). "We and others have developed several distinct GPC2-CARs for patients with GPC2+ neuroblastoma." (PMID 41159102, 2025). "We and others identified glypican-2 (GPC2) as a target for neuroblastoma treatment." (PMID 41027430, 2025). "This work suggests that hCT3 AbTCR T cells could be beneficial for patients with naturally low levels of GPC2 in their tumors or those with GPC2-CAR-resistant neuroblastoma." (PMID 41027430, 2025). "Furthermore, we found that GPC2 inhibition inactivated Wnt/β-catenin signaling and suppressed the expression of the downstream transcription factor N-Myc, an oncogenic driver of neuroblastoma tumorigenesis." (PMID 41027430, 2025). "In neuroblastoma, GPC2 has pro-tumorigenic effects by signaling through the WNT/β-catenin pathway." (PMID 39317919, 2024). "In a neuroblastoma mouse model, anti-GPC2 CAR-T cells showed potent antitumor in vivo efficacy." (PMID 38727261, 2024). "Since tumor escape due to immunoediting is a key challenge to implementing CAR T cells in solid tumors, Tian and colleagues examined the ability of BiCisCAR T cells to overcome heterogenous antigen expression by using neuroblastoma cell lines that had CRISPR mediated ablation of GPC2 or CD276." (PMID 35968786, 2022). "Conclusively, based on these findings, Li and co-workers proposed GPC2 as a promising target and added that GPC2 targeting via nanobody-based immunotherapeutics might be favorable for neuroblastoma treatment." (PMID 35468841, 2022). "In addition, investigators demonstrated that GPC2 is required for neuroblastoma proliferation and developed a GPC2-targeting antibody-drug conjugate with significant cytotoxicity against highly expressing GPC2 neuroblastoma cells." (PMID 35233466, 2022). "Recently the GPC2 gene, which maps to chr7q, has been identified as oncogenic in neuroblastoma, and it has been suggested that the gain of chromosome 7 could be associated with GPC2 overexpression." (PMID 36175618, 2022). "Bosse KR has revealed that GPC-2 is a suitable tumor antigen in neuroblastoma." (PMID 33902495, 2021). "Indeed, a GPC2-targeted ADC obtained by conjugating a GPC2 directed antibody with pyrrolobenzodiazepine dimers resulted in being effective in neuroblastoma." (PMID 32916872, 2020). "It is reported that GPC2 could promote the proliferation of neuroblastoma cells as a result of MYCN binding to a motif of the promoter of GPC2 and gain of chromosome 7q." (PMID 33302876, 2020). "GPC2 can also be used an effective prognostic indicator for prostate cancer and neuroblastoma." (PMID 33302876, 2020). "Indeed, two new ADCs have been recently deployed to target ALK and GPC2 expressed on the surface of neuroblastoma cells." (PMID 33076448, 2020). "In neuroblastoma (NB), GPC2 was reported to be upregulated in tumor tissues and was selectively expressed on the cell surface." (PMID 39014225, 2024).
neuroblastoma (continued). "Gene expression-based exploration of the surfaceome of neuroblastoma cells identified GPC2 as a cell surface molecule that is highly expressed in neuroblastoma with low expression on normal tissue, indicating that it may be an ideal candidate for CAR T cell based immunotherapy." (PMID 30459759, 2018). "Among these are a second-generation CAR-T targeting the signaling co-receptor glypican-2 (GPC2) and a second-generation CAR-T targeting B7-H3, both well-known tumor antigens expressed by multiple pediatric cancers, including neuroblastoma." (PMID 39908652, 2025). "In neuroblastoma, the GPI-anchored oncoprotein GPC2 serves as a therapeutic target, with high expression correlating with poorer survival in high-risk patients." (PMID 39860532, 2025). "Protein abundance of KCNH1 was comparable to targets under development in neuroblastoma including NCAM1, L1CAM and CD276, and higher than other known immunotherapeutic targets such as ALK and GPC2." (PMID 38895237, 2024). "Preclinical work with a bicistronic GPC2 and B7-H3-targeted CAR shows promising results in preclinical models of neuroblastoma." (PMID 39317919, 2024). "Since combined expression of GPC2 and CD276 is observed in 95% of neuroblastoma samples, these BiCisCAR T cells have specificity for a greater proportion of cancer cells compared to single target CAR T cells." (PMID 35968786, 2022). "In detail, GPC2-redirected immunotoxins suppressed neuroblastoma growth, and consistent with this finding, VHH-based GPC2-redicted CAR-Ts also demonstrated significant antitumor activity against IMR5 cells with high levels of GPC2 expression." (PMID 35468841, 2022). "While GPC2 CARs lose cytotoxicity in the context of GPC2 ablation and CD276 lose cytotoxicity in the context of CD276 ablation, BiCisCARs retained cytotoxicity with both GPC2KO and CD276KO neuroblastoma cells." (PMID 35968786, 2022). "Here, we aimed to identify optimal CARs against glypican 2 (GPC2) or CD276 (B7-H3), which were highly but heterogeneously expressed in neuroblastoma (NB), a lethal extracranial solid tumor of childhood." (PMID 35852863, 2022). "As examples, in the PPTC dataset, GPC2 and ALK are dramatically overexpressed neuroblastoma models, as previously published, but also in multiple subsets of additional pediatric cancer histotypes, allowing for a basket trial design for preclinical testing." (PMID 31693904, 2019). "Anti-GPC2 CAR T cells demonstrated in vitro activity and in vivo clearance of human neuroblastoma xenografts." (PMID 30459759, 2018). "We previously isolated a mouse-derived monoclonal antibody (mAb) termed CT3, which binds specifically to exon 3 of GPC2, highly expressed in most neuroblastoma tissues with no expression in normal tissues except testis at both RNA and protein levels." (PMID 41027430, 2025). "The hCT3 mAbs showed similar binding to the GPC2-expressing neuroblastoma cell line IMR5, with no binding to the IMR5 GPC2 knockout cell line." (PMID 41027430, 2025). "As an oncofetal antigen, GPC2 is expressed in neuroblastoma but is mostly absent in healthy tissue, making it an excellent target for cancer therapy." (PMID 41027430, 2025). "This poses GPC2 as a promising immunotherapeutic target, with multiple groups showing anti-neuroblastoma activity in mice treated with CAR-T cells with no significant associated toxicities and clinical trial underway [NCT05650749]." (PMID 39489087, 2024). "Glypican-2 (GPC2), an oncofetal target expressed in early development that regulates cell growth and is limited in postnatal human tissues, was more recently discovered to be overexpressed in neuroblastoma." (PMID 36853475, 2023). "Due to high GPC2 expression in neuroblastomas with 7q gain and diploid MYCN, GPC2 was not one of the genes to be differentially overexpressed when comparing MYCN amplified to non-amplified tumors." (PMID 32211329, 2020).
neuroblastoma (continued). "The HSPG glypican-2 was recently shown to be highly expressed in neuroblastoma but not detectable in normal childhood tissues." (PMID 29559954, 2018). "GPC2 is highly expressed in neuroblastoma, and not detectable in healthy cells." (PMID 38727261, 2024).
brain tumors (4 papers, 2020 to 2025). "Given its expression in brain tumors, we evaluated the preclinical activity of our GPC2-chimeric antigen receptor (CAR) against MB and compared it to two existing CARs targeting GD2 and B7-H3." (PMID 41159102, 2025). "In other research has been shown that the protein GPC2 is highly differentially expressed across a variety of pediatric brain tumors, including malignant embryonal tumors and a subset of HGGs and DMGs." (PMID 36983330, 2023). "Harnessing RNA sequencing to confirm highly different expressions of Glypican 2 (GPC2) across multiple pediatric brain tumors, researchers designed GPC2-directed CAR-T cells that could safely target malignant tumors with local delivery." (PMID 38918817, 2024). "However, GPC2 was notably upregulated in MB compared to other brain tumors and healthy tissues." (PMID 41159102, 2025).